INS (insulin)
Diseases named in the same sentence as INS in open-access papers (continued):
Sharing a sentence is not in itself a finding about the gene and the disease.
metabolic disorders (continued). "To date, the concept of endothelial IR has not been clinically established because only a small number of clinical studies have shown the actual response to insulin in endothelial cells of patients with metabolic disorders." (PMID 36009329, 2022). "Prebiotics, probiotics, and postbiotics (such as SCFA) have beneficial effects on this metabolic disorder by anti-inflammatory and hypoglycemic effects and insulin regulation." (PMID 35806234, 2022). "miR-130a/b can inhibit de novo lipogenesis, but enhance lipolysis and regulate insulin sensitivity, thus being involved in metabolic diseases such as liver steatosis and T2D." (PMID 36438765, 2022). "T2D is a metabolic disorder in which chronic high levels of blood glucose result from inability of insulin to act on cells due to insulin resistance, sometimes combined with an insufficient amount of insulin production." (PMID 35397604, 2022). "IL18 promotes BAT thermogenesis predominantly through NCC and maintains glucose sensitivity and insulin signaling through IL18r, thereby mitigating metabolic disorders." (PMID 36482059, 2022). "Sal B treatment markedly ameliorated lipid, glucose, and insulin metabolism disorders in db/db mice." (PMID 35068334, 2022). "Studies have found that intestinal flora and metabolites can reverse some metabolic disorders, including high fat, tissue inflammation and low insulin sensitivity and secretion." (PMID 36618372, 2022). "In recent years AD has been increasingly viewed as a metabolic disorder, exhibiting impaired brain responses to glucose and insulin, with increased insulin and insulin-like growth factor (IGF) resistance." (PMID 35958733, 2022). "To confirm the effects of MG741 on metabolic disorder markers, we measured fasting blood glucose levels, serum levels of insulin, ALT, AST, leptin, total cholesterol, LDL-cholesterol, HDL-cholesterol, liver weight, and liver triglyceride levels." (PMID 35565930, 2022). "During pregnancy, the mother's many hormones change, weakening the ability to regulate blood sugar and reducing insulin sensitivity, and it is prone to basic metabolic disorders." (PMID 36093497, 2022). "Together, these findings further highlight the importance of regular exercise to maintain metabolic health as excess visceral fat and liver fat have been related to metabolic disease and impaired insulin sensitivity." (PMID 35854646, 2022). "It is a systematic metabolic disorder characterized by defective insulin secretion and impaired insulin, resulting in microvascular complications and hyperglcemia." (PMID 36213270, 2022). "Our previous studies, and others, have demonstrated that irisin-attenuated metabolic disorders, improved insulin sensitivity, and activated insulin signaling pathways contribute to the beneficial effects of irisin." (PMID 36297305, 2022). "Although artificial sweeteners reportedly have negligible effects on insulin levels, such ingredients (sucralose, aspartame, and saccharin) may adversely affect the gut microbiome which may indirectly impair glucose haemostasis, causing insulin resistance and contributing to metabolic disease." (PMID 36159086, 2022). "MHO has a high level of insulin sensitivity and favorable lipid characteristics, which appears to “protect” the body from developing a metabolic disorder." (PMID 35910571, 2022). "T2D is a progressive multifactorial metabolic disease, which is the result of metabolic imbalances, in particular abnormal insulin production, elevated insulin resistance, high glucagon secretion, and drop in viable β-cell content." (PMID 35899227, 2022). "l-Arabinose supplementation was reported to regulate glucose homeostasis via inhibition of hepatic gluconeogenesis and improvement of insulin sensitivity, thus suppressing elevated plasma glucose and insulin levels in metabolic disorder mice." (PMID 35428331, 2022).
metabolic disorders (continued). "The increased insulin and IGF-I levels around parturition were able to mobilize enough energy from the body reserves to prevent metabolic disorders, even during a period with deficient energy supply." (PMID 36496921, 2022). "We start by providing concepts regarding the role of insulin and insulin signaling pathways as well as the pathophysiological mechanisms that are in the genesis of metabolic diseases." (PMID 35406040, 2022). "It is caused by various reasons and is often accompanied by a series of metabolic disorders of sugar, protein, fat, water, and electrolytes in the body due to defective insulin secretion or insulin function." (PMID 36553069, 2022). "The same observations were confirmed in women affected by PCOS, indicating that myo-Ins is an effective insulin sensitizer and strengthening the idea that its administration provides a useful approach for some metabolic disorders." (PMID 36465640, 2022). "The main side effects of OLZ that got affected by HBOT were related to metabolic disorders including lipid profile, glucose and insulin levels, weight gain as well as some enzymatic changes related to metabolism such as lipase and amylase." (PMID 36590387, 2022). "Fasting, fluid resuscitation, and insulin therapy were initiated in the intensive care unit with good clinical results and progressive improvement in metabolic disorders." (PMID 35154963, 2022). "Bioinformatics analysis predicted, among others, carbohydrate metabolism disorder in dystrophic mice, as functionally proven by impaired glucose tolerance and insulin sensitivity." (PMID 35273230, 2022). "Consistently, the observed changes are known to be related to insulin sensitivity and metabolic disease and altered in PCOS per our previous work." (PMID 35800349, 2022). "A study suggested that regular exercise decreased plasma insulin levels and reduced metabolic disease." (PMID 36163183, 2022). "Diabetes is a metabolic disorder influenced by high blood sugar levels due to insufficient insulin release or synthesis." (PMID 36553074, 2022). "Sphingolipids have been connected to the progression of metabolic diseases due to their modulation of insulin signalling." (PMID 36075960, 2022). "Similar to insulin levels, the result only remained significant in metabolic disorder subjects (summary r = 0.438, 95% CI 0.149–0.653, p < 0.05) when the subgroup analysis was conducted." (PMID 36271416, 2022). "The components of this type of healthy diet can improve insulin sensitivity, increase antioxidant capacity, and reduce metabolic disorders." (PMID 36364798, 2022). "Like in humans, glucose tolerance and insulin sensitivity of mice deteriorate with age, contributing to metabolic disorders." (PMID 36010860, 2022). "Branched SCFAs can modulate the lipid and glucose metabolism in adipocytes, improving insulin sensitivity in individuals with metabolic disorders." (PMID 35458204, 2022). "T2DM is a common endocrine and metabolic disorder that is characterized by a poor response to insulin and impaired insulin secretion by pancreatic β-cells." (PMID 36362336, 2022). "IR is a metabolic disorder in which there is an impaired biological response to insulin stimulation in organs and tissues, leading to poor uptake and oxidation of glucose and a decrease in glycogen synthesis." (PMID 35865388, 2022). "It is a metabolic disease characterized by the presence of chronic hyperglycemia, which results from insufficient insulin secretion or decrease of its biological action in different tissues like skeletal muscle, liver or adipose tissue." (PMID 35801218, 2022). "ERK1/2 has been reported to be involved in many metabolic diseases by regulating inflammation, reducing lipids, and improving insulin sensitivity and glucose tolerance." (PMID 35872979, 2022).
metabolic disorders (continued). "High blood glucose is always accompanied by multiple metabolic disorders like decreased insulin secretion, imbalance of the cellular ratios of NAD+ or NAPD+, and indicative of oxidative stress." (PMID 36439691, 2022). "As human cells predominantly rely on glucose as a source of energy, and the cellular uptake of glucose is controlled by insulin, IIS or IR can be risk factors for numerous metabolic diseases in the liver, cardiovascular system, nervous system, etc.." (PMID 36497154, 2022). "Studies have shown that miRNAs play an imperative function in insulin signaling, glucose and lipid pathways, and the development of several metabolic disorders, including GDM." (PMID 36558427, 2022). "It is a metabolic disorder characterized by persistent elevation of blood glucose as a result of a defect in insulin secretion, insulin action, or both." (PMID 35651441, 2022). "DM is a group of metabolic disorders involving disturbances of carbohydrate, fat, and protein metabolism resulting from defects in insulin secretion, insulin action, or both." (PMID 35388310, 2022). "DM is a serious and incurable metabolic disease defined by high blood glucose levels produced by a relative or absolute shortage of insulin or insulin's inability to work on its target tissues." (PMID 36624877, 2022). "T2D is a multi-factorial metabolic disorder, characterized by defects in insulin secretion and/or responses, increased inflammation, compromised energy metabolism and cardiovascular abnormalities." (PMID 34575050, 2021). "These endocrine cells represent important potential targets for treatments of metabolic diseases, as their hormones are involved in controlling key physiological processes such as appetite and insulin secretion." (PMID 34887382, 2021). "DM is suggested to be a metabolic disease related to inflammation and vascular complications resulting from reduced insulin production or a decreased tissue response to insulin." (PMID 33968046, 2021). "Therapeutics improving metabolic disorders including sensitization of tissues to insulin and bariatric surgery to lose weight can in turn influence GnRH and sex hormone secretion, thus alleviating PCOS." (PMID 34122341, 2021). "Specifically, serum sclerostin was closely associated with peripheral insulin sensitivity (HOMA2-%S), thus supporting the role of skeletal muscle/bone interactions in metabolic diseases." (PMID 33671861, 2021). "Increases in total daily PA and MVPA were associated with lower fasting plasma insulin and CRP as well as heart rate, thus indicating a lower metabolic disease risk." (PMID 34122148, 2021). "Our results confirm that OLZ impairs INS-induced glucose uptake in skeletal muscle and produces lipid accumulation in HepG2 cells, suggesting a metabolic disorder in L6 and HepG2 cell lines, which can be corrected only in liver cells but not in muscle cells." (PMID 34684731, 2021). "In summary, these results suggest that fetuin-A can modulate the insulin signaling pathways, contributing to metabolic diseases." (PMID 33498410, 2021). "This was supported by the fact that infusion of GM from lean volunteers to subjects with metabolic disorders demonstrated an increase in insulin sensitivity." (PMID 34574159, 2021). "In fact, natural compounds such as genipin, resveratrol, quercetin, ursolic acid, and cinnamon have been reported to enhance insulin sensitivity and improve mitochondrial function in various preclinical models of metabolic disease." (PMID 34684871, 2021). "This review explores the dynamic structural and functional features of the MAM and summarizes the various abnormalities leading to the impaired insulin sensitivity and metabolic diseases." (PMID 34571844, 2021). "The role of IGF2BP2 in glucose tolerance, insulin sensitivity, fatty acid oxidation and the development of metabolic diseases had been reviewed recently." (PMID 33568150, 2021).
metabolic disorders (continued). "In this study, insulin-induced HepG2 cells were used to explore the effect of HSAV on metabolic disorder in vitro." (PMID 33981226, 2021). "DM is a metabolic disorder of multiple etiology characterized by chronic hyperglycemia with alterations of carbohydrate, lipid and protein metabolism due to defects in insulin secretion and/or insulin signal transduction pathway." (PMID 34358033, 2021). "This is in contrast to earlier findings from individuals with metabolic diseases with a lower BG and insulin response following the ingestion of glucose and fructose." (PMID 34836350, 2021). "Type 2 diabetes (T2D) is a multifactorial metabolic disorder characterized by insulin insensitivity and insufficient insulin secretion by pancreatic beta cells." (PMID 33544077, 2021). "Central insulin signaling represents a fundamental relation between cognitive and metabolic diseases." (PMID 34690937, 2021). "All of these data showed that FA oxidation plays a crucial role in blood glucose homeostasis and its alteration contributes to impair the secretion of insulin in metabolic diseases." (PMID 33844166, 2021). "Fetuin-A performs deleterious functions in these metabolic diseases precisely because it can develop injury to pancreatic β cells, which are responsible for insulin production." (PMID 33807959, 2021). "Insulin sensitizers are used to overcome metabolic disorders that result in a reduced level of insulin." (PMID 34572109, 2021). "It is associated with various physiological and pathological processes, such as metabolic disease, insulin synthesis, cardiovascular disease, inflammation, and carcinogenesis." (PMID 34356303, 2021). "DKA can affect the function of the hypothalamus-pituitary-thyroid axis directly or indirectly due to various factors such as relatively insufficient insulin secretion and metabolic disorders, thus affecting thyroid function." (PMID 34188679, 2021). "Chronic inflammation modulates a plethora of immunologic and inflammatory mediators that impact insulin-targeting organs, leading ultimately to various metabolic disorders including insulin resistance." (PMID 34230537, 2021). "Intraperitoneal injection of galanin induced increased FSH levels and decreased LH and insulin levels, thus alleviating the metabolic disorders in PCOS rat." (PMID 34122341, 2021). "Evidence of an insulin-sensitising role of HIFs in metabolic disease complicates the overall effect of HIF activation in fatty liver disease, which is typically associated with insulin resistance." (PMID 34692739, 2021). "This reduction in muscle mass, mediated by myostatin, facilitates the appearance of metabolic disorders, such as resistance to insulin and accumulation of fat in the liver, since skeletal muscle is the main source of glucose-dependent glucose uptake." (PMID 33807959, 2021). "Further, it is anticipated to improve metabolic disorders by improving fasting glucose and insulin concentrations." (PMID 34203398, 2021). "The relative level of total ω6-PUFA was higher and that of ω9-MUFA was lower in HF/C M than F, indicative of metabolic disorders including liver steatosis, higher glucose, and insulin levels." (PMID 33398027, 2021). "MiR-103 and 107 have been previously identified as negative regulators of insulin sensitivity, and increased hepatic expression has been observed in both humans and murine models of metabolic disease and/or high fat diet consumption." (PMID 33445606, 2021). "Protein-tyrosine phosphatise 1B (PTP1B) is a protein involved in the insulin signalling pathway and a negative regulator in metabolic disorders." (PMID 34827690, 2021). "Recent studies indicate that the ceramide to sphingolipid ratio is essential in regulating insulin action in metabolic disease." (PMID 34943862, 2021). "This line of evidence supports the role of receptor protein tyrosine phosphatases (RPTPS) in insulin signaling and secretion, and consequently in the pathophysiology of metabolic diseases like T2DM." (PMID 34071721, 2021).
metabolic disorders (continued). "MLT influences metabolic disorders including diabetes via the control of insulin release in vivo and in vitro." (PMID 33748504, 2021). "Meanwhile, low levels of HIF2α activation in metabolic diseases appear to have a beneficial effect on insulin sensitivity and glucose handling." (PMID 34692739, 2021). "Treatment with coffee extract attenuated high-fat diet-induced metabolic disorders and decreased body weight, adipose tissue, and plasma concentrations of glucose, free fatty acid, cholesterol and insulin in mice." (PMID 34832525, 2021). "Strategies to protect total islet β-cell mass, insulin production, and insulin secretion are therefore sought to prevent onset of such metabolic diseases." (PMID 34572374, 2021). "DM is a group of metabolic disorders characterized by increased levels of blood glucose, resulting from defects in insulin secretion or insulin action, or both." (PMID 34063006, 2021). "DM is a complex metabolic disease characterized by chronic hyperglycemia, resulting from defects in insulin secretion, insulin action, or both, and involves a wide range of genetic and environmental factors." (PMID 33817432, 2021). "Combined with HFD, the metabolic disorder seemed to aggravate, the fasting insulin and glucose, HOMA-IR, and TG were significantly elevated, and HDL-C was reduced in the L2 group, compared with the C group." (PMID 34257691, 2021). "Due to limited studies on the CAV1 polymorphism, more researches are warranted to evaluate the impacts of insulin pathways on caveolin-related metabolic disease." (PMID 34001235, 2021). "T2DM is a metabolic disorder characterized by high blood glucose levels resulting from altered insulin secretion or action." (PMID 34068221, 2021). "Identifying novel signaling pathways affecting brain insulin signaling can help to reveal new potential treatment options for metabolic disorders." (PMID 33946318, 2021). "The carotid body functions as a sensor of glucose and insulin, and surgical removal of its nerves prevents the development of diet-related metabolic diseases." (PMID 33705641, 2021). "Third, we also studied the effects of IH derived EVs on insulin sensitivity in naïve adipocytes; In addition to cardiovascular consequences, OSA has been linked with metabolic disorders." (PMID 34070558, 2021). "A relationship between changes in insulin signaling and inflammation in metabolic diseases has been investigated." (PMID 34440853, 2021). "In particular, data have shown that early-life exposures and their effects on lifetime metabolic disease are mediated by DNA methylation alterations in the gene pathways involved in the endocrine function, metabolism, and insulin responses." (PMID 33743080, 2021). "Exercise-induced hepatokines plays a role in regulating energy balance by improving insulin sensitivity, inflammation, and mitochondrial function, thereby contributing to the improvement of metabolic disorders." (PMID 33498410, 2021). "It is a group of metabolic disorders characterized by chronic hyperglycemia due to defects in insulin secretion, insulin action, or both." (PMID 34299638, 2021). "Metabolic diseases impair brain health and cognitive function, and insulin signaling affects the hippocampus’s molecular cascades of flexibility, learning, and memory." (PMID 34311759, 2021). "Since poor blood glucose management is a hallmark of metabolic diseases, we also explore the variable TMAO effects on insulin resistance and insulin production." (PMID 34445033, 2021). "Metabolic systems within skeletal muscle that are prone to dysregulation in the context of metabolic diseases include glucose metabolism, insulin signaling, mitochondrial function, and lipid metabolism." (PMID 33433056, 2021). "PRAS40 plays an important role in metabolic disorders and multiple cancers, and is known to be an insulin-regulated inhibitor of mTORC1." (PMID 34016143, 2021).